UGT1A1 (UDP glucuronosyltransferase family 1 member A1)
Diseases named in the same sentence as UGT1A1 in open-access papers (continued):
Sharing a sentence is not in itself a finding about the gene and the disease.
neutropenia (continued). "As our study was a small cohort retrospective study and was not adjusted for other factors (e.g., starting dose of nal-IRI), further investigation is needed to determine the effect of UGT1A1*1/*28 or *1/*6 on neutropenia related to nal-IRI+5-FU/LV." (PMID 36836140, 2023). "The rate of grade ≥3 neutropenia was 30.8% in the UGT1A1*1/*1 group and 50.0% in the heterozygous group (p = 0.24)." (PMID 36836140, 2023). "If UGT1A1*1/*6 and *1/*28 are the risk factor of neutropenia induced by nal-IRI, reconsidering the administration dose of nal-IRI by UGT1A1 status will be necessary." (PMID 36836140, 2023). "Based on these reports, patients with heterozygous UGT1A1, especially *1/*6, appear to be at increased risk of nal-IRI-induced neutropenia." (PMID 36836140, 2023). "Patients with the UGT1A1*6 polymorphism showed a significantly higher incidence of grade III–IV diarrhea (9/34 patients [26.47%], p = 0.012) and grade III–IV neutropenia (14/34 patients [41.18%], p = 0.044) after the irinotecan-containing regimen." (PMID 36239106, 2022). "Given these premises, this study evaluated the incidence of neutropenia following pre-therapeutic irinotecan dose modifications driven by the UGT1A1 genotype." (PMID 35207692, 2022). "Studies also demonstrated that in Asian cancer patients, the combination of UGT1A1*6 and UGT1A1*28 polymorphisms was associated with an increased risk of IRI-induced neutropenia." (PMID 35340156, 2022). "The genetic polymorphism of uridine diphospho glucuronosyltransferase 1A1 (UGT1A1*28) has been reported to reduce the UGT1A1 enzymatic activity and result in irinotecan-induced neutropenia." (PMID 35548363, 2022). "In 247 patients with advanced gastrointestinal cancers undergoing irinotecan-based chemotherapy, we prospectively performed UGT1A1*28 genotyping and we analyzed the incidence of severe neutropenia according to genotype-guided dose reductions." (PMID 35207692, 2022). "Among patients who had any of the UGT1A1*6, UGT1A7*3 or UGT1A9*22 variants, 13 suffered grade III–IV neutropenia and 23 suffered grade III–IV diarrhea." (PMID 36239106, 2022). "The risk factors for severe neutropenia in patients receiving mFOLFIRINOX were a low baseline WBC count and heterozygosity for UGT1A1*28 or UGT1A1*6 polymorphism." (PMID 36114233, 2022). "On the other hand, with a pre-therapeutic median irinotecan dose reduction equal to 40%, we observed among 27 UGT1A1*28 homozygous carriers a 39% rate of grade ≥ 3 neutropenia." (PMID 35207692, 2022). "Compared with UGT1A1*28 homozygous patients, the rate of grade ≥ 3 neutropenia was significantly lower (OR vs*28/*28 genotype = 0.28, 95% CI: 0.12–0.67; p = 0.004)." (PMID 35207692, 2022). "Among 163 patients carrying the UGT1A1*1*28 or UGT1A1*1*1 genotypes treated with upfront reduced doses of irinotecan following clinical judgment, 25 (15.3%) developed grade ≥ 3 neutropenia." (PMID 35207692, 2022). "At normal doses, the alarming role of UGT1A1*6 on neutropenia and diarrhea is greater than UGT1A1*28." (PMID 35340156, 2022). "Although only two patients with UGT1A1 single heterozygous type were enrolled in this study, one of them experienced grade 4 neutropenia." (PMID 34019214, 2021). "One CUA with model-based study from France and one CEA with model-based study from the US were performed to evaluate the cost-effectiveness of UGT1A1 screening before prescribing irinotecan to prevent severe neutropenia in metastatic colorectal cancer." (PMID 34600523, 2021). "According to UGT1A1 genotype, grade 4 neutropenia and febrile neutropenia occurred in 46.2 and 25.6 %, respectively, of patients with UGT1A1 *1/*6 or *1/*28 single heterozygous type in the previous QUATTRO study." (PMID 34019214, 2021). "UGT1A1 IMs or PMs receiving larger belinostat doses also had increased incidences of higher-grade neutropenia and thrombocytopenia." (PMID 33805415, 2021).
neutropenia (continued). "Some studies confirmed that UGT1A1*28 and UGT1A1*6 are related to chemotherapy-related diarrhea and neutropenia induced by irinotecan." (PMID 34567559, 2021). "The strongest correlations with severe neutropenia and diarrhea were found among UGT1A1*28 homozygotes with irinotecan doses ≥ 180 mg/m2, particularly with doses ≥ 250 mg/m2." (PMID 33805415, 2021). "In conclusion, the incidence of neutropenia in this study indicated that advanced PC patients with UGT1A1-DV tolerate irinotecan administered at the initial dose of ≤ 120 mg/m2." (PMID 33386925, 2021). "Others have also showed a correlation between UGT1A1*28 and neutropenia, diarrhoea and vomiting (p < 0.01)." (PMID 33228198, 2020). "Our results showed that combined analysis of UGT1A1*28 and *6 polymorphisms and ABCC2 c.3972C > T were closely related with neutropenia toxicity in Thai colorectal cancer patients." (PMID 32778670, 2020). "Although the maximum tolerated dose of IRI was confirmed to be 150 mg/m2 for patients with UGT1A1 homozygous (*28/*28, *6/*6, or *28/*6), grade 3 or higher neutropenia was observed in 62.5% of these patients during the first cycle." (PMID 31203527, 2020). "Particularly in Caucasian patients, UGT1A1*28 seems to be a good predictor of neutropenia (at all CPT-11 doses) and diarrhea (at CPT-11 dose of 125 mg/m2)." (PMID 32758288, 2020). "For UGT1A1*28 and UGT1A1*6, the incidence of 3~4 grade neutropenia and 3~4 grade diarrhea significantly declined in both the dose reduction and non-reduction groups." (PMID 32264830, 2020). "In contrast, there were significant differences between grade 1–4 neutropenia and patients with UGT1A1*28 at the second cycle." (PMID 32778670, 2020). "Among the 20 cases of UGT1A1*6 G/A + A/A, nine cases (45.0%) had grade 3~4 delayed-onset diarrhea and eight cases (40.0%) experienced grade 3~4 neutropenia." (PMID 32264830, 2020). "Grade 4 neutropenia and febrile neutropenia during the early cycles were higher in patients heterozygous for UGT1A1 (*28/*1, *6/*1) in comparison to wild type (*1/*1)." (PMID 31203527, 2020). "Several studies have investigated the relationship of UGT1A1*28 and severe neutropenia and diarrhea during irinotecan treatment." (PMID 32778670, 2020). "Among the 86 patients, there were 66 cases of UGT1A1*6 G/G, of which six cases (9.1%) experienced grade 3~4 delayed-onset diarrhea, and 10 cases (15.2%) had grade 3~4 neutropenia." (PMID 32264830, 2020). "In conclusion, combination of UGT1A1*28 and *6 and ABCC2 c.3972C > T genotype are associated with the occurrence of grade 1–4 and severe neutropenia in Thai patients with metastatic colorectal cancer who receive irinotecan-based chemotherapy." (PMID 32778670, 2020). "The common (5% or higher) severe AEs were decreased white blood cell count (11% and 16%), neutropenia (15% and 32%), anemia (21% and 24%), and anorexia (1.6% and 11%) in the UGT1A1 WT and UGT1A1 SH groups." (PMID 32666389, 2020). "In conclusion, this meta-analysis suggested that the UGT1A1*6 polymorphism linked with IRI-induced adverse reaction with CRC, especially increase the incidence of serve late-onset diarrhea and neutropenia." (PMID 32936306, 2020). "Among hematological AEs, the incidence of neutropenia was higher in the UGT1A1 SH group than in the UGT1A1 WT group, but the difference was not significant (32% vs. 15%; p = 0.109)." (PMID 32666389, 2020). "Among these patients with UGT1A1 polymorphism, six had been administered PEG-G-CSF, two after the development of grade 3 neutropenia, and four prophylactically." (PMID 32345249, 2020). "UGT1A1 activity is the main factor determining cytotoxicity and AEs of irinotecan, and the US Food and Drug Administration has approved UGT1A1 genotyping to predict irinotecan-induced severe diarrhea and neutropenia." (PMID 31856912, 2019).
neutropenia (continued). "A meta-analysis demonstrated a significant increase in grade 3/4 neutropenia for UGT1A1 *28/*28 patients at medium (150–250 mg/m2) (OR 3.22, p = 0.008) and high doses (>250 mg/m2) (OR 27.8, p = 0.005)." (PMID 30646508, 2019). "Today, a genetic test for UGT1A1, especially the UGT1A1*6 and UGT1A1*28 mutations, is performed before treatment with CPT-11, because use of CPT-11 carries a high risk of adverse effects such as severe neutropenia and diarrhea." (PMID 31730632, 2019). "The active ingredient of NK012, SN-38, is metabolized by UGT1A enzymes, and polymorphisms of the UGT1A1 gene are known to be associated with an increased incidence of severe neutropenia." (PMID 30284603, 2018). "In particular, the incidence of grade 4 neutropenia was significantly higher in patients with UGT1A1*1/*6 genotype in the QUATTRO trial that evaluated GONO-triplet regimen plus bevacizumab for Japanese mCRC patients." (PMID 29721163, 2018). "Ten patients (1.8%) had UGT1A1*27 heterozygotes in this cohort, but only 2 patients suffered severe neutropenia." (PMID 28637434, 2017). "evaluating the associations of variants in the UGT1A1 gene with the safety and efficacy of irinotecan monotherapy for pancreatic cancer in a Japanese cohort showed higher rates of neutropenia and anorexia in patients with UGT1A1 *6 and/or *28." (PMID 29340058, 2017). "More mutational alleles of UGT1A1*6/*28 and DPYD*5 were also revealed to had increased incidence of severe neutropenia (P = 0.008)." (PMID 28637434, 2017). "Of which, one patient with heterozygous UGT1A1*28 and UGT1A1*6 experienced grade IV neutropenia and grade III diarrhea, and had the largest dose-normalized AUC of SN-38." (PMID 27871319, 2016). "One patient with heterozygous UGT1A1*6 experienced grade 3 febrile neutropenia, and 2 patients with heterozygous UGT1A1*28 experienced grade 3 febrile neutropenia and grade 4 neutropenia." (PMID 26163340, 2015). "One of nine patients with wild-type UGT1A1*6 experienced grade 4 thrombocytopenia, and 1 patient with heterozygous UGT1A1*6 experienced grade 4 leukopenia and neutropenia." (PMID 26163340, 2015). "The occurrence of severe neutropenia during treatment with irinotecan (CPT-11) is associated with the *6 and *28 alleles of uridine diphosphate glucuronosyltransferase 1A1 (UGT1A1)." (PMID 24932285, 2014). "The data from the present study of patients with gynecological cancer also indicates a role for the UGT1A1*6/*6 genotype in neutropenia, similar to these previous studies of other types of cancers." (PMID 24932285, 2014). "There are differences between Caucasian and Asian populations in frequencies of UGT1A variants, and UGT1A1*6 reportedly associates strongly with severe neutropenia especially among Asian patients." (PMID 25175642, 2014). "Since variants of not only UGT1A1, but also other genes, including UGT1A7, UGT1A9, ABCB1 and ABCC2, have been reported to be involved in the occurrence of CPT-11-induced severe neutropenia, rare variants of these genes should be investigated in the future." (PMID 24932285, 2014). "Five patients (including 2 patients with an UGT1A1 homozygous genotype) experienced grade 4 neutropenia (< 7 days duration), and 1 patient experienced grade 4 thrombocytopenia and grade 4 anemia." (PMID 24337768, 2014). "A recessive model of inheritance best explained the significant difference in incidence of G4 neutropenia with respect to the UGT1A1 gene (P=0.037)." (PMID 24932285, 2014). "In particular, patients bearing UGT1A1*28 (TA7/7) had a high possibility of developing severe neutropenia and diarrhea." (PMID 24759962, 2013). "One of the landmark studies of the role of UGT1A1 in irinotecan toxicity included only 63 patients, of whom six had the clinical outcome of interest (grade 4 neutropenia)." (PMID 23570317, 2013). "Published meta-analyses have demonstrated dose-dependent associations between UGT1A1*28 genotype and IRI-induced neutropenia or diarrhea." (PMID 23516488, 2013).
neutropenia (continued). "Patients who are homozygous for UGT1A1*28 have less capacity to eliminate SN38, and many studies have reported a significant increase risk of grade 3-4 neutropenia and/or diarrhea in those patients treated by irinotecan for metastatic colorectal cancer." (PMID 24212636, 2011). "UGT1A1*28/*28 was predictive for haematologic toxicity (OR=6.27, 95% CI=1.09–36.12; P=0.04), specifically for neutropenia alone (OR=6.40, 95% CI=1.11–37.03; P=0.038) or together with diarrhoea (OR=18.87, 95% CI=2.14–166.67; P=0.008)." (PMID 20628391, 2010). "Febrile neutropenia, one of the side effects of irinotecan, can be predicted by the uridine diphosphate glucuronosyl transferase (UGT)1A1 *28 genotype." (PMID 19536092, 2009). "In this study, we assessed the contribution of baseline bilirubin level to statistical models for predicting neutropenia based on age, gender, and UGT1A1 genotype among patients receiving first-line irinotecan-based chemotherapy for mCRC." (PMID 19639031, 2008). "The most severe neutropenia grade during cycle 1, after cycle 1, and over all cycles is summarized by UGT1A1 TA indel genotype and chemotherapy arm." (PMID 19639031, 2008). "Among all patients combined, UGT1A1 genotype significantly predicted the rate of grade 4 neutropenia." (PMID 19639031, 2008). "In the pivotal ASCENT trial, the authors noted a higher rate of grade ≥ 3 SG‐related neutropenia, febrile neutropenia, anemia, and diarrhea in women with the UGT1A1*28/*28 genotype and advised that individuals with the UGT1A1*28/*28 genotype should be monitored closely." (PMID 40936312, 2026). "In conclusion, UGT1A1*6 and ABCC2 -24C > T polymorphisms may serve as predictors of irinotecan-induced neutropenia, while UGT1A1*6 and SLCO1B1 521T > C are associated with improved progression-free survival in Thai patients." (PMID 41385496, 2025). "UGT1A1*6 and ABCC2 -24C > T variants emerge as potential predictors of irinotecan-induced neutropenia, while UGT1A1*6 and SLCO1B1 521T > C may serve as markers of prolonged PFS in Thai patients." (PMID 41385496, 2025). "Nevertheless, a combined analysis of UGT1A1*6 and UGT1A1*28 may also serve as a potential biomarker for irinotecan-induced neutropenia in the Thai population, which still requires validation through further research." (PMID 41385496, 2025). "Nonetheless, after applying the Bonferroni correction, the association between UGT1A1*28 and neutropenia was no longer statistically significant." (PMID 41385496, 2025). "Prescreening for UGT1A1 genotype is then not strictly necessary but patients with a homozygous *28/*28 genotype should be closely monitored for an increased risk of neutropenia." (PMID 39796075, 2024). "Indeed, the results reported by Chen and colleagues (for Irinotecan 180 mg/m2) showed that grades 3–4 neutropenia occurred for 15% of the patients with wild-type UGT1A1 (1*/1*) and 30.8% of the patient with heterozygous UGT1A1 genotype (1*/28*)." (PMID 37932443, 2024). "In addition, a higher incidence of severe neutropenia was observed in patients with homozygous alterations in the liver enzyme uridine diphospho-glucuronyl transferase (UGT1A1) in the ASCENT trial." (PMID 39518062, 2024). "al. reported that grade ≥3 neutropenia occurred more frequently in patients who were heterozygous for UGT1A1*6 allele, while not for *28 allele in gastric cancer patients treated with nal-IRI." (PMID 36836140, 2023). "Our study indicated that patients with UGT1A1*1/*6 or *1/*28 may be prone to neutropenia, though further study is needed." (PMID 36836140, 2023). "Moreover, three previous studies revealed that patients homozygous for UGT1A1*28 showed a high risk (OR = 20.09,50 6.04,51 and 8.61,52 vs genotype TA6/TA6) of severe neutropenia." (PMID 36308049, 2023). "Although no studies have directly demonstrated this, the higher frequency of neutropenia in Asians may be influenced by racial differences in UGT1A1." (PMID 36836140, 2023).
neutropenia (continued). "Especially when the dose is ≥180 mg/m2, UGT1A1*28 is related to neutropenia and diarrhea." (PMID 35340156, 2022). "Only 1 patient with a heterozygous UGT1A1*28 genotype developed grade 3 neutropenia." (PMID 35864467, 2022). "Furthermore, the UGT1A1 gene is accountable for the metabolism of SN-38, which is an active metabolite of irinotecan, and different variations of UGT1A1 (such as UGT1A1*6 and UGT1A1*28) increase myelosuppression, such as serious neutropenia." (PMID 36309754, 2022). "Patients with UGT1A1 *28/*28 genotype versus those with 1/*28 and *1/*1 genotypes had higher rates of grade ≥3 SG-related neutropenia (59% vs 47% and 53%), febrile neutropenia (18% vs 5% and 3%), anemia (15% vs 6% and 4%), and diarrhea (15% vs 9% and 10%), respectively." (PMID 36038616, 2022). "The limited number of UGT1A1*28/*28 carriers in the current study does not allow to draw firm conclusions on irinotecan dose thresholds and risk of severe neutropenia." (PMID 35207692, 2022). "This Korean irinotecan pharmacokinetics study might also explain our finding that UGT1A1*6, UGT1A7*3, and UGT1A9*22 were associated with severe diarrhea or neutropenia." (PMID 36239106, 2022). "We included UGT1A1 IM group in the multivariate analysis in spite of statistical insignificance (p = 0.231), because previous studies showed that IM group was related to neutropenia." (PMID 35267552, 2022). "Homozygous or double-heterozygous UGT1A1*6 or *28 is associated with higher incidence of severe neutropenia but not diarrhea." (PMID 32666389, 2020). "Guangxi Zhuang patients of metastatic colorectal cancer with UGT1A1*28 mutations showed a higher risk of 3~4 grade diarrhea as compared to those with wild-type UGT1A1*28 which did not increase the risk of grade 3~4 neutropenia." (PMID 32264830, 2020). "Meanwhile, UGT1A1*28 TA6/7 was unlikely to increase the risk of grade 3~4 neutropenia (χ2 = 2.844, p = 0.092)." (PMID 32264830, 2020). "Neutropenia occurred more frequently, but not significantly, in patients with UGT1A1 polymorphism than in patients without UGT1A1 polymorphism (p = 0.09)." (PMID 32758288, 2020). "Patients with UGT1A1 polymorphisms tended to experience grade 3 or 4 neutropenia more frequently than those with wild-type UGT1A1 (p = 0.09, no significance)." (PMID 32758288, 2020). "However, two studies used narrow health outcome measures such as neutropenia avoided and one study suggested a conditional cost-effectiveness of UGT1A1 testing depending on the treatment efficacy of irinotecan dose reduction." (PMID 30256829, 2018). "For example, the incidence of grade 4 neutropenia is significantly higher, while median PFS and OS are significantly shorter in non-small cell lung cancer patients receiving irinotecan with UGT1A1*6 homozygous mutation compared to the heterozygous mutation or wild-type allele." (PMID 30453583, 2018). "UGT1A1*28 heterozygotes (OR = 2.263, 95%CI 1.395–3.670), UGT1A1*28 homozygotes (OR = 5.910, 95%CI 1.138–30.682) and UGT1A1*6 homozygotes (OR = 4.737, 95%CI 1.946–11.533) were the independent predictive factors of severe neutropenia." (PMID 28637434, 2017). "In brief, only UGT1A1*6 and UGT1A1*28 variants were associated with irinotecan-induced neutropenia, but not with diarrhea." (PMID 28637434, 2017). "Thus, patients with homozygous or heterozygous UGT1A1*28 and treated with irinotecan commonly developed dose limiting neutropenia and late diarrhea." (PMID 27871319, 2016). "Hence, we developed a new predictor for irinotecan pharmacokinetics and neutropenia, based on in vivo phenotyping of an individual's UGT1A1 activity." (PMID 26808671, 2016). "Homozygosity or double heterozygosity for UDP-glucuronosyl transferase 1A1 (UGT1A1) polymorphisms (UGT1A1*28 and UGT1A1*6) may relate to increased serious adverse events, such as neutropenia and diarrhea, in patients treated with an irinotecan-based regimen." (PMID 28007025, 2016).